INSR (insulin receptor)
Diseases named in the same sentence as INSR in open-access papers (continued):
Sharing a sentence is not in itself a finding about the gene and the disease.
liver cancer (8 papers, 2014 to 2025). An epithelial or non-epithelial malignant neoplasm that arises from the liver. "In contrast, estrogens have little effect on hepatic GLUT4 and insulin receptor in male rats, but estrogens increase level of insulin receptor in HepG2, a liver cancer cell line." (PMID 26491440, 2015). "We examined the effects of Fen on the insulin receptor pathway using Western blotting to determine whether it increases glucose uptake in liver cancer cells by modulating insulin signaling." (PMID 40070568, 2025). "This study underscores the pivotal roles of phosphatase and tensin homolog (PTEN), insulin receptor (IR), and IGF-1 receptor (IGF1R) in controlling liver metabolism, systemic adiposity, and liver cancer progression." (PMID 40115165, 2025). "Specifically, 50 isoforms of GA were studied in relation to specific inhibition of RTKs such as insulin receptor (IR), insulin-like growth factor (IGFR), VEGFR1, VEGFR2, and estrogen receptor in liver cancer cells." (PMID 29872510, 2018).
neuroblastoma (8 papers, 2012 to 2025). Neuroblastoma (NB) is the most common solid, extracranial childhood tumor. "In contrast, all the RAS/MAPK pathway-altered neuroblastoma lines expressed the insulin receptor, which is highly homologous to IGF1R, to a similar extent as MCF7 cells, except CHP-212." (PMID 39001383, 2024). "Anaplastic lymphoma kinase (Alk) is a receptor tyrosine kinase of the insulin receptor super-family that functions as oncogenic driver in a range of human cancers such as neuroblastoma." (PMID 32917927, 2020). "INSR expression shows a correlation with degree of apoptosis and dedifferentiation in human neuroblastomas, and is co-expressed with insulin-like growth factor 1 receptor." (PMID 30786925, 2019). "Moreover, μ-calpain degrades insulin receptor substrates (IRS), major substrates of insulin signaling, in human neuroblastoma cells and prostate epithelial cells." (PMID 22536436, 2012).
osteosarcoma (8 papers, 2013 to 2023). A usually aggressive malignant bone-forming mesenchymal neoplasm, predominantly affecting adolescents and young adults. "We developed a new prognostic risk model for osteosarcoma based on 7 glycolytic genes (INSR, FAM162A, GLCE, ADH5, G6PD, SDC3, HS2ST1) by bioinformatics." (PMID 36387908, 2022). "Our study also found high expression of INSR in MG-63 osteosarcoma cells, which correlates with high levels of glycolysis in tumor cells." (PMID 36387908, 2022). "A risk model based on seven glycolytic genes (INSR, FAM162A, GLCE, ADH5, G6PD, SDC3, HS2ST1) can effectively evaluate the prognosis of osteosarcoma, and in vitro experiments also confirmed the important role of INSR in promoting OS migration." (PMID 36387908, 2022). "The WB results showed that INSR protein expression was higher in human MG-63 osteosarcoma cells than in human hFOB1.19 osteoblasts (P<0.01)." (PMID 36387908, 2022). "We specifically chose to treat osteosarcoma cells with a dual inhibitor, because the insulin receptor can activate the same downstream signaling pathways as IGF1R, therefore providing cells a way to circumvent single inhibition of IGF1R." (PMID 23688189, 2013). "Moreover, mRNA expression of IGF1 and IGF2 in osteosarcoma cells were increased, while the insulin receptor (INSR) and insulin receptor substrate 1 (IRS1) genes were both downregulated." (PMID 37755271, 2023). "al described the relevance of insulin receptor isoform A (IR-A) and hybrid-receptors (HR), which consist of one α and one β subunit IR heterodimer and one α and one β subunit IGF1R heterodimer in osteosarcoma samples." (PMID 25170759, 2014). "Indeed, it was shown in osteosarcoma cells that dual inhibition of IGF-1R and insulin receptor is more effective than IGF-1R inhibition alone." (PMID 26563243, 2016).
diabetic retinopathy (7 papers, 2013 to 2023). "While we have not studied pathological angiogenesis, our data may be relevant to disease states associated with altered insulin receptor biology, such as diabetic retinopathy, and future work should address this possibility and its translational potential." (PMID 34460911, 2021). "Our findings establish IGFBP-3 as a pivotal regulator of the insulin receptor/TNFα pathway and a potential therapeutic target for diabetic retinopathy." (PMID 24695399, 2014). "Rats administered STZ have shown reduced insulin receptor signaling in the retina, especially in retinal endothelial cells, which may contribute to the early progression of diabetic retinopathy." (PMID 26035391, 2015). "Neural retinal cell changes occur early in diabetic retinopathy, and may be attributed to a reduced insulin receptor signaling in the diabetic retina." (PMID 24167638, 2013). "In addition, the vascular endothelial growth factor signaling pathway that involving many target proteins, such as INSR, NOS3, PTGS2, and vascular endothelial growth factor A (VEGFA), plays a key regulatory role in diabetic retinopathy." (PMID 32265717, 2020).
Hypoinsulinemia (7 papers, 2008 to 2022). A decreased concentration of insulin in the blood. "Improving the insulin receptor signaling pathway is likely an important mechanism for brown adipose tissue to obtain glucose more efficiently in the setting of cold-induced hypoinsulinemia." (PMID 24915042, 2014). "Additionally, when fetal liver growth is decreased in FGR pregnancies, a decrease in IGF1 concentrations is often observed, as well as an upregulation of the fetal liver INSR in response to fetal hypoinsulinemia." (PMID 36293384, 2022). "We hypothesize that the patient may have had a transient insulin receptor defect or hypoinsulinemia due to organic acids." (PMID 24637313, 2014). "Conversely, in streptozotocin-diabetic rats, correction of hypoinsulinemia with insulin treatment did not affect renal insulin receptor numbers." (PMID 36289636, 2022).
Hypomagnesemia (7 papers, 2017 to 2025). An abnormally decreased magnesium concentration in the blood. "Insulin upregulates TRPM6 activity; thus, patients with lower insulin receptor activity are more susceptible to hypomagnesemia." (PMID 38511086, 2024). "It has been reported that hypomagnesemia can lead to a defective activity of tyrosine kinase and can modify insulin sensitivity by influencing the activity of the insulin receptor after binding or by influencing the intracellular signaling and processing." (PMID 32085495, 2020).
prediabetes (7 papers, 2015 to 2025). "In prediabetic obese mice, virally induced IFN-γ (using murine cytomegalovirus) drives the progression from prediabetes to T2D by causing insulin resistance in skeletal muscles through downregulation of the insulin receptor." (PMID 36262060, 2023). "Since insulin exhibits its effect through its receptor, we investigated the gene expression of the insulin receptor (IR), which was found to be 1.18-fold higher in prediabetes cases and 0.85-fold in the newly diagnosed T2D group compared to the control group." (PMID 36004027, 2022). "We consider that the alterations in the intracellular Ca2+ handling of vascular smooth muscle cells (VSMCs) and the impairment of the insulin receptor signaling pathway may contribute to the etiology of vascular diseases in prediabetes and MetS." (PMID 40556956, 2025). "The etiology of vasculopathy in prediabetes and MetS may share common mechanisms involving alterations in the insulin receptor (InsR) signaling pathway, which affect both ECs and VSMCs." (PMID 40556956, 2025). "This cross-sectional study aimed to investigate the independent risk factors for prediabetes, considering the contribution of genetic factors (TCF7L2-rs7903146, IRS1-rs1801278, INSR-rs3745551, CDKN2A-rs10811661, and FTO-rs9939609), socio-economic status, and lifestyle factors." (PMID 26334876, 2015). "Therefore, the study was designed to investigate both genetic (TCF7L2-rs7903146, IRS1-rs1801278, INSR-rs3745551, CDKN2A-rs10811661, and FTO-rs9939609) and environmental factors for prediabetes in a Vietnamese population." (PMID 26334876, 2015).
Autoimmunity (6 papers, 2016 to 2025). The occurrence of an immune reaction against the organism's own cells or tissues. "In the context of autoimmunity in T1D, oxPTMs and their immunological consequences have been studied extensively; however, cellular response to oxidized insulin regarding INSR and GLUT4 regulation, metabolism, proliferation, and glucose uptake were omitted." (PMID 39378614, 2024). "Then we thought that the patient may have an autoimmune IRS due to autoantibodies against INSR (type B IRS) or exogenous insulin." (PMID 40696585, 2025). "We have recently shown that insufficient signaling through the IGF1/insulin receptor could initiate autoimmunity and contribute to RAab production." (PMID 36429105, 2022).
brain tumor (6 papers, 2010 to 2025). "Here, we targeted the IGF pathway using ceritinib, an off-target inhibitor of the IGF1 receptor (IGF1R) and insulin receptor (INSR), in a pediatric patient with an unclassified brain tumor and a notch receptor 1 (NOTCH1) germline mutation." (PMID 31480400, 2019). "Of note is the fact that both insulin receptor and IGF-1R were repeatedly shown to be associated with brain tumour development, proliferation and response to therapy in humans." (PMID 20436918, 2010). "The typical receptors utilized in nanoparticle-based drug delivery for brain tumors includes transferrin receptor mediated transcytosis, low-density lipoprotein receptor-mediated transcytosis, insulin receptor-mediated transcytosis and nicotinic acetylcholine receptor-mediated transcytosis." (PMID 39998776, 2025).
cervical cancer (6 papers, 2014 to 2025). A primary or metastatic malignant neoplasm involving the cervix. "Previous studies have also suggested that cosmosiine inhibits cell migration in cervical cancer, insulin receptor phosphorylation, adiponectin secretion, inflammation, and oxidative stress." (PMID 35998194, 2022). "Insulin receptor and insulin-like growth factor 1 (IGF-1) are expressed in most cancer cells, and IGF-1 can stimulate invasion and proliferation of cervical cancer cells." (PMID 25963193, 2015). "The objective of this study was to investigate which isoform of the insulin receptor is expressed in the HeLa cervical cancer cell line and to analyze the role of IRS-1 and IRS-2 in the signaling pathway of the insulin receptor and in regulating the proliferation and migration of HeLa cells (HPV+)." (PMID 36975518, 2023).
leukemia (6 papers, 2011 to 2025). A malignant (clonal) hematologic disorder, involving hematopoietic stem cells and characterized by the presence of primitive or atypical myeloid or lymphoid cells in the bone marrow and the blood. "In conclusion, our research offers significant findings regarding the expression profiles of LMNA/C and INSR transcript variants in PBMCs among individuals with leukemia." (PMID 38731097, 2024). "The objective of this study was to assess the expression of LMNA/C and INSR transcript variants in peripheral blood mononuclear cells (PBMCs) of leukemia patients to investigate their potential as diagnostic biomarkers." (PMID 38731097, 2024). "The INSR transcript variants, IR-A and IR-B, were assessed in PBMC samples collected from both healthy individuals and individuals diagnosed with leukemia." (PMID 38731097, 2024). "It remains possible that INSR is abona fide leukemia gene; regardless, we strongly believe that a biologist wanting to use the output of CATAPAULT would also want to know about the specificity of the predictions." (PMID 24715959, 2013). "Additionally, the abnormal signaling of INSR can contribute to metabolic changes in leukemia cells, further propelling disease progression." (PMID 38731097, 2024). "We are led to suspect this is at least partly explained by the high node degree of INSR, and not specific “guilt by association” of INSR with known leukemia genes." (PMID 24715959, 2013). "The complex interplay between the INSR and tyrosine kinase receptors, such as growth factor receptors, and RAS pathway activation has significant implications for leukemia pathogenesis." (PMID 38731097, 2024). "We measured the expression of genes coding RTKs: FLT3, KIT exclusively in leukemia cell lines, PDGFRa, AXL in NB, NTRK1, FGFR3, INSR, ROR2, and RET in both NB and leukemia cells by qRT-PCR, which were top-scoring RTK-coding genes among leukemia and NB cell lines." (PMID 34944663, 2021).
thyroid (6 papers, 2005 to 2022). "Indeed, in TC cells and tissue specimens, both IGF-1 receptor (IGF-1R) and insulin receptor (IR) are often overexpressed, representing an early event in thyroid carcinogenesis." (PMID 29184536, 2017). "In accordance with these findings, insulin receptor expression was found to be upregulated in hypofunctioning benign thyroid adenomas that have lost a differentiated function such as iodine uptake, indicating that overexpression of insulin receptor occurs early in thyroid tumorigenesis." (PMID 35255873, 2022).
viral infection (6 papers, 2015 to 2023). "IFN-gamma released after virus infection downregulates the insulin-receptor expression of skeletal muscle, and viral infection enhances the progression of T2DM in obesity, thus worsening hyperglycemia." (PMID 36013384, 2022). "Another study showed that expression of the cell surface insulin receptor is modulated by wMel infection, reducing the susceptibility of mosquito cells to DENV and ZIKV (Zika virus) infection." (PMID 33853965, 2021). "In addition to the PI3K/Akt pathway, E1A can also associate with the insulin receptor substrate (IRS-1) to increase Akt phosphorylation, which contributes to adenovirus-transformed phenotypes and modulates viral infection in an Akt-dependent manner." (PMID 26515462, 2015). "Moreover, following insulin binding, the insulin receptor translocates to the nucleus, where it plays a crucial role in regulating the transcription of various immune-related genes, including pathways involved in viral infections." (PMID 37795081, 2023). "While the insulin receptor is not a known entry receptor for DENV, this study illustrates that Wolbachia has the potential to modulate expression of cell membrane proteins and thereby alter the permissiveness of these cells to viral infection." (PMID 33853965, 2021).
vitamin D deficiency (6 papers, 2015 to 2025). A nutritional condition produced by a deficiency of VITAMIN D in the diet, insufficient production of vitamin D in the skin, inadequate absorption of vitamin D from the diet, or abnormal conversion of vitamin D to its bioactive metabolites. "Multiple factors, including impaired post-insulin receptor signaling, poor dietary habits, physical inactivity, metabolic acidosis, anemia, vitamin D insufficiency, chronic inflammation, oxidative stress, and adipokine imbalance, influence it." (PMID 41048435, 2025). "Vitamin D deficiency itself also led to decreased LC3 II levels in the liver and decreased insulin receptor staining in the ovaries." (PMID 31509973, 2019).
asthma (5 papers, 2019 to 2024). "We have shown that downregulation of the insulin receptor (INSR) signaling pathway and loss of differentiation in AECs are conserved features of asthma in adults and children." (PMID 39156016, 2024). "Both variants were encoded for the insulin receptor (INSR) gene region that was suggestively associated with asthma risk." (PMID 33628342, 2021). "The PPI network analysis, among other genes, identified INSR to be more closely related to severe asthma, as it was more interactive in this phenotype." (PMID 32512817, 2020). "This study demonstrated an important role of INSR (insulin receptor) in asthma." (PMID 32512817, 2020). "The combined interaction scores resulted in higher interactions for the genes STAT3, AGO2, COL1A1, CLCN6, and KSR for moderate asthma and JAK2, INSR, ERBB2, NR3C1, and PTK6 for severe asthma." (PMID 32512817, 2020). "For example, in severe asthma, the combined interaction scores for the STAT3, AGO2, COL1A1, CLCN6, and KSR1 genes yielded a higher interaction for the moderate asthma phenotype, and the JAK2, INSR, ERBB2, NR3C1, and PTK6 genes were more interactive for the severe asthma phenotype." (PMID 32512817, 2020).
cholangiocarcinoma (5 papers, 2019 to 2021). A carcinoma that arises from the intrahepatic biliary tree (intrahepatic cholangiocarcinoma) or from the junction, or adjacent to the junction, of the right and left hepatic ducts (hilar cholangiocarcinoma). "In cholangiocarcinoma (CCA), the interaction between cancer cells and CAFs mediated by insulin-like growth factor 2 (IGF2), insulin receptor (IR) and IGF1 receptor (IGF1R) was found to regulate ERL resistance." (PMID 30927928, 2019).
diabetic neuropathy (5 papers, 2011 to 2022). A chronic, pathological complication associated with diabetes mellitus, where nerve damages are incurred due to diabetic microvascular injury involving small blood vessels that supply these nerves, resulting in peripheral and/or autonomic nerve dysfunction. "The Insulin Receptor Signaling Pathway has also been implicated in neuropathic pain as evidenced in numerous studies of diabetic neuropathy." (PMID 35057068, 2022). "Studies have indicated a connection between GSK-3 and an increase in insulin receptor phosphorylation in patients with diabetic neuropathy and experimental models of diabetic neuropathy." (PMID 35291879, 2022). "One important finding is the link between GSK3 and an increase in insulin receptor phosphorylation in diabetic neuropathy subjects and diabetic neuropathy." (PMID 31382613, 2019).
glucose metabolism disorders (5 papers, 2023 to 2025). "The epidermal growth factor receptor (EGFR) is known to be a key factor in glucose metabolism disorders due to its ability to inhibit insulin receptor activity upon activation." (PMID 40863931, 2025). "Glucose metabolism disorder and IR in the hippocampus of diabetic rats could be thus closely related to CIs, dysfunctional glucose metabolism, and brain metabolic stress, which might damage cognitive-motor functioning, playing a role in the destruction of the insulin receptor system." (PMID 37970434, 2023).
hyperlipidemia (5 papers, 2015 to 2022).
liver disease (5 papers, 2014 to 2025). "The INSR tyrosine kinase is hyperphosphorylated in fibrotic liver disease in humans and rodents in the location of the HSCs, as was shown by visualization of αSMA distribution." (PMID 40022609, 2025). "Previous studies have corroborated the decreased INSR expression in kidney diseases, while others have validated the increase of the receptor in liver diseases, highlighting the involvement of stellate cells in the process." (PMID 38768139, 2024). "In addition, the presence of hepatitis B virus may retain insulin receptors intracellularly at the endoplasmic reticulum and impede insulin receptor signaling, which could prevent compensatory liver regeneration and lead to liver disease progression." (PMID 31200528, 2019).